PDGFRB (platelet derived growth factor receptor beta)
Diseases named in the same sentence as PDGFRB in open-access papers (continued):
Sharing a sentence is not in itself a finding about the gene and the disease.
tumor (continued). "We further showed that in this IS tumor, PDGFRB protein was consistently activated (phosphorylated), strongly suggesting E472D be an activating mutation in maintaining aberrant PDGFRB signaling in IS." (PMID 29113426, 2017). "Taken together, we show that pericyte α6β1-integrin regulates tumour blood vessels by both controlling PDGFRβ and basement membrane architecture." (PMID 28289267, 2017). "Due to the high affinity and specificity for PDGFRβ, the ZPDGFRβ affibody was predominantly distributed on PDGFRβ+ pericytes and accumulated in tumor grafts." (PMID 29182023, 2017). "Abnormal structures of tumor blood vessels make PDGFRβ-positive pericytes attractive target cells for drug delivery." (PMID 29182023, 2017). "The recruitment of α-smooth muscle actin (ASMA)- and PDGFRβ-positive pericytes was similar in the three tumor types." (PMID 28231806, 2017). "EphB4 signaling can be induced by trans interactions with its cognate ligand, EphrinB2, typically expressed in the tumor microenvironment on endothelial; or by cis interactions with PDGFRβ expressed on RMS tumor cells." (PMID 28817624, 2017). "Steller EJ showed that PDGFRB signaling in mesenchymal-like tumor cells (as colorectal cancer cells) contributes to invasion and liver metastasis formation." (PMID 28435517, 2017). "Genetic ablation of pericyte α6β1-integrin correlates with reduced pericyte investment to tumour blood vessels, changes in BM architecture and reduced PDGFRβ expression levels and PDGF-BB-mediated downstream signalling." (PMID 28289267, 2017). "al detected an anti-tumor effect in term of tumor liquefaction, metabolic and clinical response of imatinib mesylate 800mg daily; he supposed an activity mediated by PDGFRβ-inhibition." (PMID 28775967, 2017). "The levels of NOTCH1 and PDGFRB in GBM were significantly higher than those in non-tumor controls (P values were 0.0085 or 0.019, respectively), whereas PDGFRA levels were similar (P value was 0.58), consistent with previous reports." (PMID 27863440, 2016). "Phosphorylation analysis showed that a substantial proportion of PDGFRβ molecules were phosphorylated in Panc02 tumour tissue." (PMID 27150562, 2016). "We localized PDGFRβ expression in various tumour xenografts and found that the Panc02 tumour expressed PDGFRβ at a high level as compared with other tumour types." (PMID 27150562, 2016). "Previous studies showed that either genetic or pharmacological targeting of PDGFRβ or PDGFRα inhibited self-renewal, survival, tumor growth and invasiveness of GBM CSC." (PMID 27344175, 2016). "IHC staining was performed to determine the expression of Beclin 1, PTEN, and PDGFRβ in archived tumor samples from 18 of 33 patients who received treatment and were evaluable for response." (PMID 27213589, 2016). "In a previous study by Preusser et al18 sunitinib showed significant improvement of clinical symptoms and disease stabilization to an ONB patient, who had positive staining of PDGFRB in the tumor tissue specimen by immunohistochemistry." (PMID 27149458, 2016). "Tumor specimens were double stained for PDGFRβ and a representative marker of carcinoma cells, E-cadherin." (PMID 27128408, 2016). "Among the top hits were genes involved in cellular matrix remodeling and tumor invasion and migration, including platelet-derived growth factor receptor beta (PDGFRβ), which was found to be the highest-ranking receptor protein genome-wide." (PMID 27128408, 2016). "The epidermal growth factor receptor (EGFR) and the platelet-derived growth factor receptor β (PDGFRβ) are hallmarks in GBM with driving roles in tumor progression." (PMID 26461476, 2015). "In untreated tumor lysates activated PDGFRB was expressed at well detectable levels in all patient-derived xenografts and activated PDGFRA in those where its gene is amplified." (PMID 26599335, 2015). "10% of EGFP-positive cells in these tumors express PDGFRβ, showing that tumor pericytes can also be derived from bone marrow." (PMID 26137396, 2015).
tumor (continued). "In Western blot analyses regorafenib resulted in a pronounced reduction of both total and phosphorylated PDGFRB protein levels in three tumor lysates analyzed." (PMID 26599335, 2015). "The poor efficacy of the p15-RGR peptide-engrafted liposomes towards tumor B16-F1 was attributed to differences in PDGFRβ expression levels in the tumor model used in this study." (PMID 25126543, 2014). "When PDGFRB, age, tumor size, and tumor number were combined, the sensitivity increased to 82.7%, and the specificity increased to 88.5%." (PMID 24801713, 2014). "Two cpACs had faint stromal staining for VEGF and PDGFRα whereas; PDGFRβ had distinct strong stromal tumor staining in 92% (11/12) with faint positive cytoplasmic staining and rare membranous staining of the neoplastic cells in 75% (9/12)." (PMID 24423144, 2014). "PDGF-BB activates pericytes by the tyrosine kinase receptor PDGFRβ, which likely serve as important gatekeepers against cancer progression and metastasis by stabilizing the tumor vasculature." (PMID 25483099, 2014). "The clones with PDGFRβ activation were also resistant to MEK inhibition, implying that activation of PDGFR bypasses the tumor dependence on RAF signaling entirely." (PMID 24743024, 2014). "We also were able to determine that ensheathment of CD31-positive endothelial cells by PDGFRβ-positive pericytes is reduced in tumor vessels in pericyte-NG2ko mice." (PMID 23925489, 2014). "While not all candidates validated by immunoblotting, we did observe phosphorylation of both ErbB2 and PDGFRβ in at least some of the recurrent tumours, suggesting that RTK signalling was actively occurring." (PMID 24457046, 2014). "In 183 NMIBC patients, the level of urinary PDGFRB was increased in patients with a large tumor size (>3 cm; 329.6±22.10 ng/mL, n = 46) compared with those with a small tumor size (≤3 cm; 290.4±11.08 ng/mL, n = 139) (P = 0.0907)." (PMID 24801713, 2014). "Since Imatinib targets both PDGFRα and PDGFRβ while Sunitinib and Regorafenib only target PGDFRβ, we anticipated that Imatinib would be the most effective inhibitor at suppressing tumor cell migration." (PMID 25253994, 2014). "TMPRSS2-ERG was found to associate with these factors in a manner predicting a poor outcome of the patient (high tumor stromal expression of PDGFRβ, hyaluronan, von Willebrand factor and low stromal expression of Caveolin-1)." (PMID 24505269, 2014). "The role of PDGFRβ in various pathophysiological mechanisms, including both tumor development and treatment outcome, makes the receptor an attractive structure for molecular targeting and imaging approaches." (PMID 22791264, 2013). "PDGFRβ is expressed in various solid tumors and is involved in important biological processes, such as cell proliferation and regulation of the tumor interstitial pressure." (PMID 22791264, 2013). "Sunitinib and sorafenib are PDGFRβ tyrosine kinase inhibitors in wide clinical application that directly inhibit tumor cell proliferation and angiogenesis." (PMID 24649266, 2013). "Typically, PDGFRα is highly expressed by tumour cells and PDGFRβ is preferentially expressed by vascular endothelial and mural cells within tumours." (PMID 23638177, 2013). "Chordoma is a rare slow-growing tumor arising from remnants of the notochord, which often expresses PDGFRβ." (PMID 24359404, 2013). "To test for tumoral Ad5ROBO4 mediated EC cell type specificity, we co-stained tumor sections with antibodies cognate for pericyte, desmin, PDGFRβ, and NG2, or inflammatory cell, CD45, antigens." (PMID 24376772, 2013). "In the current study, we found PDGFRα to be expressed in all tumor cells of all canine TC samples, while PDGFRβ was primarily expressed in the tumor stroma by IHC." (PMID 22630170, 2012). "Expression of PDGFRβ in tumor cells was restricted to only 16% of tumor samples, which is consistent with a previous study that found 15 of 77 samples to be positive for this receptor." (PMID 22630170, 2012).
tumor (continued). "Complementary to these in vitro observations, morphine in clinically used doses increased desmin- and PDGFRβ-positive cells in the tumor vasculature of mice, suggestive of increased proliferation and/or recruitment of vessel-associated pericytes." (PMID 22315595, 2012). "Then, blockade of this PDGFRβ-dependent feedback loop by sorafenib enhanced the anti-tumor sensitivity of rapamycin in vitro and in an immunocompetent orthotopic rat model of HCC." (PMID 22428038, 2012). "In contrast PDGFRβ expression was found in only a few tumor samples but was evident in the stroma of all tumor specimens." (PMID 22630170, 2012). "Similar to the case of TC, we identified expression of PGDFRα in the tumor cells of all AGASACA samples and PDGFRβ in the tumor stroma by IHC." (PMID 22630170, 2012). "Colocalization of vascular endothelial growth factor receptor 2 (VEGFR-2) and platelet-derived growth factor receptor beta (PDGF-Rβ) reduces pericyte ensheathment of tumor vessels." (PMID 22253625, 2012). "In conclusion, our findings confirmed that activation of PI3K/AKT and MAPK pathway through a PDGFRβ-dependent feedback loop compromises the anti-tumor activity of rapamycin in HCC." (PMID 22428038, 2012). "Another potential target over-expressed on tumor pericytes is platelet derived growth factor receptor beta (PDGFR-β)." (PMID 21385454, 2011). "Aside from inhibitors, preclinical approaches have also been conducted to develop PDGFRβ-based DNA vaccine aiming at preventing tumor development." (PMID 22205974, 2011). "In patients with a Gleason score 4–6 or Gleason score 7 tumor, only about 20% of the tumors showed stroma PDGFRβ staining, but it was considerably more common in cases with Gleason score 8–10 tumors." (PMID 20505768, 2010). "Some studies have shown that FGF-2 and hypoxia up-regulate PDGFR in the tumor vasculature, but the mechanism by which PDGFRβ is up-regulated by tumor cells needs further investigations." (PMID 27713269, 2010). "PDGFRβ has been identified as an important drug target in tumor therapy, based on the overexpression of PDGF-B by many solid tumors." (PMID 27713269, 2010). "Presence of PDGFRβ staining in the fibroblast- like tumor stroma was significantly positively correlated with large tumor size, advanced stage, high Gleason score and high vessel density." (PMID 20505768, 2010). "The functional relationship between Src inhibition and regulation of the receptor tyrosine kinase platelet-derived growth factor receptor beta (Pdgfrb) as well as the fibronectin receptor integrin alpha 5 (Itga5) has been commonly observed in tumour cells." (PMID 21152443, 2010). "PDGF-B and PDGFRβ are mainly expressed in the developing vasculature in both normal and pathological conditions, including tumor angiogenesis." (PMID 27713269, 2010). "In human glioblastoma, PDGFRα is expressed by tumor cells and PDGFRβ is expressed by ECs of the newly-formed blood vessels." (PMID 27713269, 2010). "Perivascular PDGFRβ expression in the tumor area was also positively correlated with advanced stage, tumor vessel density and high Gleason score (data not shown)." (PMID 20505768, 2010). "It was considerably more common to find PDGFRβ expression in the normal prostate tissue stroma when a Gleason score 8–10 tumor was present elsewhere in the organ compared to if the tumor was Gleason score 4–6." (PMID 20505768, 2010). "PDGFRβ expression by pericytes is necessary for their recruitment and integration in the wall of tumor vessels." (PMID 27713269, 2010). "Data from both experimental models and clinical samples have identified important functions of PDGFRβ on pericytes and fibroblasts in the tumor stroma." (PMID 20505768, 2010). "PDGFRβ expression in tumor cells was found in more than two thirds of the cases, with strong and homogeneous distribution." (PMID 27713269, 2010). "Of note, 80 of 91 (88%) assessable tumours were positive for PDGFRα, whereas 47 of 67 (70%) assessable tumours expressed PDGFRβ." (PMID 19904263, 2009).
tumor (continued). "It is plausible that PDGFRβ acts as a pivotal target mediating tumor–stroma crosstalk." (PMID 41601676, 2026). "Notably, the restored fluorescence intensity shows a direct correlation with cellular PDGFRβ expression, highlighting the nanoprobe's potential for guiding tumor diagnosis and treatment." (PMID 41884335, 2026). "Sunitinib blocks PDGFRβ activation and diminishes these tumor-promoting effects." (PMID 41601676, 2026). "Overexpression of the studied markers was found to be significantly correlated with high tumor grade (G3-4) (PDGFRα,β) and significant tumor burden: the extent of tumor venous thrombosis (PDGFRβ), pN+ stage (PDGFRα), and M+ stage (PDGFRβ), as well as adrenal metastases (PDGFRβ)." (PMID 40434293, 2025). "PDGFRL, a specific PDGFRβ agonist, has been suggested to exert a tumor-suppressive effect." (PMID 41155410, 2025). "PDGFRB immune cell infiltration scores were calculated for each tumor using the R software package." (PMID 40128057, 2025). "Similarly, toceranib, initially developed as an antiangiogenic compound like sunitinib, inhibits VEGFR and PDGFRβ, while also exerting direct anti-tumor effects by targeting KITr." (PMID 39858283, 2025). "Instead, this selectivity arises because tumor cells and tumor-associated stroma often show constitutive activation of RTK signaling, whereas normal glandular epithelium may express PDGFRβ but remains functionally inactive." (PMID 41472102, 2025). "Notably, we found NES+ and SOX2+ tumor cells in closer proximity to PDGFRβ+ regions, in comparison to MAP2+ cells." (PMID 40562749, 2025). "Given the aggressive nature of AGASAC and the limited success of conventional therapies, understanding the role of PDGFRβ in AGASAC could provide additional support for the use of RTK inhibitors in this tumor type." (PMID 41472102, 2025). "Our findings indicate that PDGFRβ expression varies among tumor types, possibly reflecting differences in tumor differentiation, and that distinguishing these subtypes may aid in AGASAC diagnosis and in selecting adjunctive treatments." (PMID 41472102, 2025). "Targeted therapies against PDGFRβ could offer new avenues for treating metastatic GC by reducing tumor angiogenesis and improving drug efficacy." (PMID 40282535, 2025). "In a study of 51 dogs, we examined the protein PDGFRβ on tumor cells." (PMID 41472102, 2025). "Future studies involving larger, multi-institutional cohorts are warranted to confirm whether PDGFRβ expression correlates with growth pattern or tumor differentiation in AGASACs." (PMID 41472102, 2025). "Chronic-phase PDGFRB-rearranged neoplasms are typically sensitive to TKIs such as imatinib." (PMID 41278291, 2025). "Expression of PDGFRβ in neoplastic stromal compartments (CAFs and vasculature) may further provision the use of TKIs, as these drugs may be effective also on the tumor microenvironment." (PMID 41472102, 2025). "We also observed a significant correlation of PDGFRα and PDGFRβ overexpression with high tumor grades (G3-4) and significant tumor burden: the extent of tumor thrombosis (only PDGFRβ), pN+ (only PDGFRα), and M+ (only PDGFRβ) stages, including metastases to the adrenal glands (PDGFRβ)." (PMID 40434293, 2025). "PDGFRβ signalling enhances tumor cell survival and promotes a more aggressive phenotype, which can contribute to the failure of chemotherapy, through mechanisms that involve PPAR-γ, a nuclear receptor that regulates genes involved in cell differentiation, lipid metabolism, and inflammation." (PMID 40282535, 2025). "In addition to its expression at different clinical stages, the differential expression of PDGFRB in tumor and standard tissue samples was analyzed." (PMID 40128057, 2025). "PDGFRβ expression scores showed variable distributions across tumor histotypes." (PMID 41472102, 2025). "In this context, inhibitors targeting PDGFRB could potentially be employed to suppress tumor progression in patients exhibiting characteristics of this cluster." (PMID 39762212, 2025).
tumor (continued). "One of the growth factors expressed in the tumor stroma is PDGFRβ." (PMID 39081320, 2024). "Furthermore, we investigated the expression profiles of miRNAs potentially involved in the progression of MASH in non-tumor areas of the livers of PDGFRβ knockout mice." (PMID 39394459, 2024). "This transformation could be associated with the expression levels of genes such as PDGFRB, PGF, JUN, and NR4A1, which play crucial roles in tumor development, angiogenesis, and cell proliferation." (PMID 39484208, 2024). "A different, but very promising therapeutic approach, which raised attention during the past decade, uses nanocarriers with a cyclic peptide binding specifically to PDGFRβ or PDGFRβ affibodies for the specific delivery targeting agents to the tumor site (referred to as “homing”)." (PMID 38980580, 2024). "In advanced MASH, the reduction of PDGFRβ signaling in aHSCs, may prevent further pathological progression to tumor formation in KO mice." (PMID 39394459, 2024). "Pharmacological inhibition of PDGFRB impaired tumor cell invasion induced by ITGA11-positive CAFs." (PMID 39335478, 2024). "Therefore, the present study investigated the pathological role of PDGFRβ signaling in the development of hepatic fibrosis and tumor formation in a diabetic MASH model." (PMID 39394459, 2024). "Paraffin sections of omental tumors from all treatment groups were analyzed for expression of CD31 and platelet-derived growth factor receptor b (PDGFRb) on the tumor vasculature using multispectral immunofluorescence (mIF) imaging after staining with specific mAbs." (PMID 39372930, 2024). "Notably, these effects possibly include stromal PDGFRβ in the primary tumors, as well as in the astrocytes of the metastatic tumor microenvironment." (PMID 38980580, 2024). "HRD tumors are enriched with immunogenic epithelial cells, FGFR1+PDGFRβ+ myCAFs, M1 macrophages, tumor reactive CD8+/CD4+ Tregs, whereas HRP tumors are enriched with HDAC1‐expressing epithelial cells, indolent CAFs, M2 macrophages, and bystander CD4+/CD8+ T cells." (PMID 39136172, 2024). "In BC, ITGA11/PDGFRB + CAFs displayed tumor-promoting features, though their expressions in BC may be relatively small and weak association with strSPARC." (PMID 39335478, 2024). "In addition, as the vascularization of subcutaneous tumor xenografts is different to that of the primary tumor grafts, we attempted to evaluate the PDGFRβ-targeted tracer in animals with primary HCC." (PMID 37256321, 2023). "Moreover, OV cell-derived PDGFB was the primary source that activated PDGFRB in CAFs, indicating tumor cells promoted CAF formation." (PMID 37658364, 2023). "In some cancers, endothelial PDGF-BB recruits pericytes onto angiogenic vessels by activating PDGFRβ, while tumor cell–derived PDGF-BB attracts pericytes to migrate from vessels through a chemoattractant mechanism with vessel-disassociated pericytes becoming CAFs." (PMID 36856115, 2023). "Interestingly, PDGFRB/PDGFB are in closer proximity to disease genes in the Basal-like subnetwork further supporting evidence for its role in tumor aggressiveness." (PMID 37200395, 2023). "In this study, we developed a novel [68Ga]Ga-radiolabeled affibody conjugate by targeting PDGFRβ on tumor vessels, and validated the potential for this conjugate as an alternative PET tracer for visualizing primary HCC tumor lesions in both rats and rhesus monkeys." (PMID 37256321, 2023). "Next, CPL304110 selectivity was analyzed on seven kinases; the results showed that CPL304110 had the highest activity against kinases that share homology with FGFRs (KDR and PDGFRβ) and others that play an important role in tumor development and progression (AURKA, FLT3, IGF1R, JAK2, and TRKA)." (PMID 38282676, 2023).